PCDH8 (protocadherin 8)
Description:
Calcium-dependent cell-adhesion protein (By similarity). May play a role in activity-induced synaptic reorganization underlying long term memory (By similarity). Could be involved in CDH2 internalization through TAOK2/p38 MAPK pathway. In hippocampal neurons, may play a role in the down-regulation of dendritic spines, maybe through its action on CDH2 endocytosis (By similarity).
Synonyms: PAPC; ARCADLIN
Tractability: Antibody: its Gene Ontology location is reachable by antibodies, with high confidence; UniProt places it where antibodies can reach, with medium confidence; UniProt predicts a signal peptide or a membrane-spanning region. PROTAC: its protein half-life has been measured.
Gene: Protein-coding gene on chromosome 13 (52,842,889 to 52,848,641, reverse strand). Ensembl gene ENSG00000136099.
Subcellular location: Cell membrane; Cell projection, dendrite; Presynaptic cell membrane; Postsynaptic cell membrane
Gene Ontology:
Molecular function: cell adhesion molecule binding; calcium ion binding
Biological process: cell-cell adhesion; cell-cell signaling; cell adhesion; chemical synaptic transmission; homophilic cell-cell adhesion; modulation of chemical synaptic transmission; regulation of synaptic membrane adhesion
Cellular component: plasma membrane; synapse; dendrite; glutamatergic synapse; membrane; postsynaptic membrane; presynaptic membrane; Schaffer collateral - CA1 synapse
Genetic constraint (gnomAD): Loss-of-function variants: 36 observed, 41.47 expected, observed/expected ratio (o/e) 0.87, 90% interval 0.66 to 1.15. The synonymous counts are far from expectation, so gnomAD's model fits this gene poorly and the ratio says little. Missense variants: 1,493 observed, 1,270.9 expected, observed/expected ratio (o/e) 1.17, 90% interval 1.12 to 1.23. Synonymous variants: 775 observed, 598.3 expected, observed/expected ratio (o/e) 1.3, 90% interval 1.22 to 1.38.
Homologues: Orthologues: dog PCDH8 (96% identical), rabbit PCDH8 (96% identical), pig PCDH8 (96% identical), guinea pig PCDH8 (95% identical), rat Pcdh8 (95% identical), mouse Pcdh8 (94% identical), chimpanzee PCDH8 (90% identical), macaque PCDH8 (90% identical), tropical clawed frog pcdh8 (57% identical), tropical clawed frog pcdh8l (39% identical), tropical clawed frog pcdh8.2 (39% identical), zebrafish PCDH8 (39% identical). Paralogues in human: PCDH18 (35% identical), PCDH17 (29% identical), PCDH19 (29% identical), PCDH10 (29% identical), PCDHB15 (27% identical), PCDHGA12 (27% identical), PCDHGA2 (26% identical), PCDHGA3 (26% identical), PCDHGA4 (26% identical), PCDHGA5 (26% identical), PCDHAC2 (26% identical), PCDHGA6 (26% identical), and 49 more.
Diseases named in the same sentence as PCDH8 in open-access papers:
PCDH8 is named in the same sentence as 65 diseases in open-access papers, as found by Europe PMC text mining. Sharing a sentence is not in itself a finding about the gene and the disease. The quoted sentences say what the papers report.
breast carcinoma (6 papers, 2011 to 2023). "The loss of protocadherin 8 (PCDH8) expression correlates with breast carcinoma cell progression." (PMID 37957639, 2023). "For example, PCDH8 is genetically or epigenetically silenced in breast cancer and mantle cell lymphoma." (PMID 29075151, 2017). "For instance, PCDH8 has been identified as a driver gene with promoter hypermethylation, in accordance with a previous report that this gene might be a candidate tumor suppressor gene for breast cancer." (PMID 23579546, 2013). "Hypermethylation of PCDH8 has been previously reported in RCC (58%) as well as in mantle cell lymphoma, breast carcinoma and gastric cancer, including para-carcinomic but not normal gastric tissue." (PMID 24454902, 2014).
glioma (6 papers, 2018 to 2024). A benign or malignant brain and spinal cord tumor that arises from glial cells (astrocytes, oligodendrocytes, ependymal cells). "For example, miRNA-182-5p negatively modulated protocadherin 8 and affected the proliferation and invasion in glioma." (PMID 35287547, 2022). "In glioma, PCDH8 might function as a biomarker for early detection and prognosis, its expression level being directly associated with glioma progression." (PMID 38368303, 2024). "Furthermore, STAT3-mediated activation of miR-182-5p had been shown to upregulate the proliferative and invasive capacities by directly targeting PCDH8 in glioma cells." (PMID 30927925, 2019). "Therefore, further experiments should clarify whether the Wnt signaling pathway is downregulated in PCDHGC3 overexpressing gliomas and whether the silencing of PCDHGC3 would lead to increased tumor growth, as has been shown for PCDH8." (PMID 35897674, 2022).
gastric cancer (3 papers, 2014 to 2024). A primary or metastatic malignant neoplasm involving the stomach. "In gastric cancer, PCDH8 hypermethylation was associated with lymph node metastasis that could be indicative poorer survival outcome." (PMID 24454902, 2014). "In gastric cancer, PCDH8 promotes invasion and metastasis through enhanced interaction with extracellular matrix receptors, possibly through upregulation of laminin subunit gamma-2." (PMID 38368303, 2024). "PCDH8 is an integral membrane protein that acts as a tumor suppressor in several types of cancer 29-31 and is involved in the metastasis of gastric cancer." (PMID 34234863, 2021).
esophageal squamous cell carcinoma (2 papers, 2014 to 2024). Esophageal squamous cell carcinoma (ESCC) is a type of esophageal carcinoma (EC) that can affect any part of the esophagus, but is usually located in the upper or middle third. "In esophageal squamous cell carcinoma, PCDH8 is regulated by miR-200c and functions as a regulator of metastasis." (PMID 38368303, 2024). "Within the same gene cluster as PCDH8 there resides PCDH17 and PCDH20 that are both hypermethylated and homozygously deleted in esophageal squamous cell carcinoma and lung cancer respectively." (PMID 24454902, 2014).
hypopharyngeal carcinoma (2 papers, 2020 to 2021). Carcinoma, predominantly squamous cell, arising from the epithelial cells of the hypopharynx. "PCDH8 may serve as a useful prognostic biomarker and potential therapeutic target for patients with hypopharyngeal carcinoma." (PMID 33369468, 2020). "In a clinical trial, PCDH8 was inhibited in tumor tissues when compared with that in non-tumor tissues, particularly in patients with advanced hypopharyngeal carcinoma, suggesting that PCDH8 could be a prognostic biomarker and target for the treatment of this type of cancer." (PMID 34234863, 2021).
lymph node metastasis (2 papers, 2014 to 2020). "PCDH8 methylation was also found in peri-lesional tissues, but not in normal gastric tissue, and was associated with lymph node metastasis." (PMID 33369468, 2020). "PCDH8 methylation was observed in alls cell lines and 55.38% of the primary tumor, but not in normal gastric mucosa, and was associated with lymph node metastasis." (PMID 33369468, 2020).
ovarian carcinoma (2 papers, 2021 to 2024). A malignant neoplasm originating from the surface ovarian epithelium. "Our method proposed PCDH8 and BAZ2A as novel missense driver genes in ovarian carcinoma." (PMID 38195844, 2024). "Moreover, PCDH8, a protein coding that acts as a cell adhesion molecule, and BAZ2A having DNA binding activity, were suggested as missense novel genes in ovarian cancer." (PMID 38195844, 2024).
schizophrenia (2 papers, 2012 to 2017). A major psychotic disorder characterized by abnormalities in the perception or expression of reality. "PCDH8 has been shown to be involved in synaptic plasticity of dendritic cells and represents a linkage to schizophrenia." (PMID 28993767, 2017). "Multiple genes encoded by chromosome 13 have been suggested to contribute to schizophrenia susceptibility, including DAOA, 5-HTR2A, KPNA3 and KPNB3, ESD, ATXN8OS, KFL5, EFNB2, and PCDH8." (PMID 22214315, 2012).
breast tumours (1 paper, 2015). "However, it is worth noting that to our knowledge this is the first time that promoter methylation in CCDC8, HOXD3, PCDH8, PENK, STAT3, SFRP2 and WIFI has been described in primary breast tumours." (PMID 26052355, 2015).
cervical squamous cell carcinoma (1 paper, 2024). A squamous cell carcinoma arising from the cervical epithelium. "However, PCDH8 expression did not change in cervical squamous cell carcinoma, endocervical adenocarcinoma, cholangiocarcinoma, kidney renal clear cell carcinoma, kidney renal papillary cell carcinoma, prostate adenocarcinoma, and uterine corpus endometrial carcinoma." (PMID 38368303, 2024).
kidney cancer (1 paper, 2014). Primary or metastatic malignant neoplasm involving the kidney. "From this analysis 4 genes (FBN2, PCDH8, BNC1 and SFRP1) stand out as either particularly strong epigenetic biomarkers of kidney cancer or as significant predictors of patient outcome." (PMID 24454902, 2014).
liver cancer (1 paper, 2020). An epithelial or non-epithelial malignant neoplasm that arises from the liver. "PCDH8 is often inactivated by promoter methylation in liver cancer and can serve as a valuable diagnostic biomarker for early detection and for predicting an unfavorable clinical feature." (PMID 33369468, 2020).
metastatic tumors (1 paper, 2022). "have believed that laminin subunit γ2 (LAMC2) encoding adherent laminin, significantly increased the number of liver metastatic tumors when protocadherin-8 (PCDH8) was overexpressed in GC cells." (PMID 36439439, 2022).
Pan (1 paper, 2024). "Pan-carcinoma analysis revealed a distinct difference in PCDH8 expression between tumor and noncancerous samples in THCA." (PMID 38368303, 2024).
Parkinson disease (1 paper, 2013). A progressive degenerative disorder of the central nervous system characterized by loss of dopamine producing neurons in the substantia nigra and the presence of Lewy bodies in the substantia nigra and locus coeruleus.
renal fibrosis (1 paper, 2016). A final common manifestation of a wide variety of chronic kidney diseases characterized by glomerulosclerosis and tubulointerstitial fibrosis. "The list of genes includes Fblim1, Epha2, Wisp1, Parvg, Madcam1, Mybpc2, Cdh3, Gpr56, Troap, Pstpip1, Pcdh8, Nlgn2 and Mfap4, genes that based on Pubmed and Kidney and Urinary Pathway Knowledge Base12 searches have not been previously associated with renal fibrosis." (PMID 27189340, 2016).
small cell lung carcinoma (1 paper, 2021). Small cell lung cancer (SCLC) is a highly aggressive malignant neoplasm, accounting for 10-15% of lung cancer cases, characterized byrapid growth, and early metastasis. "Additionally, PCDH8 has been found to be regulated by miR-217, which promotes apoptosis in small cell lung cancer." (PMID 34234863, 2021).
thyroid cancer (1 paper, 2024). "Based on the HPA database, their IHC results showed that the protein expression level of PCDH8 was significantly higher in thyroid cancer tissues than in normal tissues." (PMID 38368303, 2024). "In summary, PCDH8 may be involved in thyroid cancer by inhibiting immune infiltration and promoting immune escape." (PMID 38368303, 2024).
thyroid gland disorder (1 paper, 2024). A disease involving the thyroid gland. "Our results indicate that the expression of PCDH8 is significantly associated with the type of primary neoplasm focus, the PFI, history of thyroid gland disorders, methylation levels, age, race, pathologic stage, and thyroglobulin levels." (PMID 38368303, 2024). "In our study, we analyzed the Cancer Genome Atlas (TCGA) database to investigate the differential expression of PCDH8 between paired paracancerous thyroid tissues and tumor tissues and used human THCA samples to validate our analysis." (PMID 38368303, 2024). "Additionally, we explored the association between PCDH8 expression and clinical factors in THCA, revealing significant correlations with age, primary neoplasm focus type (including multifocal and unifocal), PFI, and a history of thyroid gland disorders." (PMID 38368303, 2024).
thyroid tumor (1 paper, 2024). A benign or malignant neoplasm affecting the thyroid gland. "As indicated by the ROC curve, PCDH8 effectively discerned thyroid tumors from healthy tissue (AUC = 0.747, 95% CI: 0.714–0.780), indicating its potential for identifying patients with THCA from healthy individuals." (PMID 38368303, 2024).
tumor (22 papers, 2013 to 2025). "To delve into the role of PCDH8 in the tumor immune process, we analyzed its association with immune checkpoints using the TIMER database and R package." (PMID 38368303, 2024). "Most importantly, a significant association of methylated PCDH8 level to tumor maximal diameter at diagnosis (Rs = 0.35; p = 0.028) as well as borderline significance to tumor volume (Rs = 0.32; p = 0.051) at diagnosis was identified." (PMID 36555747, 2022). "PCDH8, in turn, encodes a transmembrane adhesion and signaling molecule that acts as a tumor suppressor." (PMID 35833364, 2022). "It has also been observed that the loss of expression and high methylation of the PCDH8 promoter have been detected in the tumor cells of GC." (PMID 33369468, 2020). "PCDH8 methylation was significantly associated with the tumor size, stage, and grade (p < 0.05)." (PMID 41008642, 2025). "Methylation of adhesion/structural genes such as PCDH8 correlated with poorer OS (HR = 3.02; 95% CI = 1.54–5.90; p = 0.001), consistent with their established tumor-suppressive role." (PMID 41377897, 2025). "IHC revealed significantly elevated PCDH8 expression in THCA tumor tissue compared to paired paraneoplastic tissue." (PMID 38368303, 2024). "In terms of THCA, both paired and unpaired t-tests indicated that PCDH8 expression was significantly increased in tumor tissues." (PMID 38368303, 2024). "It acts as a tumor suppressor by directly interacting with PCDH8 and inhibiting the PI3K/AKT/mTOR signaling pathway." (PMID 39065771, 2024). "The analysis conducted using the R programming language and online web tools explored PCDH8 expression levels, prognostic, and clinical implications, and its relationship with the tumor immune microenvironment in THCA." (PMID 38368303, 2024). "We investigated the role of PCDH8 in immune infiltration and its functions in the tumor microenvironment." (PMID 38368303, 2024). "Meanwhile, the molecular biomarker analysis in the urine samples of SRM RCC patients at diagnosis demonstrated the positive correlation between methylated PCDH8 level and tumor size at diagnosis, confirming our previous report and its prognostic potential." (PMID 36555747, 2022). "Some other studies reported tumor suppressive characteristics of PCDH8, particularly inhibition of cell proliferation, migration, and induction of apoptosis, and thus this gene is inactivated by promoter methylation in some carcinomas." (PMID 36555747, 2022). "Our study indicated that miR-124-3p played a tumor suppressor by directly interacting with PCDH8 and inhibiting the activation of the phosphatidylinositol 3-kinase (PI3K)/AKT/mammalian target of rapamycin (mTOR) signaling pathway." (PMID 34234863, 2021). "Mechanism assays indicated that miR-124-3p played a tumor suppressor by directly interacting with PCDH8 and inhibiting the activation of PI3K/AKT/mTOR signaling pathway." (PMID 34234863, 2021). "PCDH8 expression was dysregulated or completely silenced in HFC tumor tissues and NFC cell lines, and the low expression was correlated to the advanced pathological stage of HFC." (PMID 33369468, 2020). "An abridged list contains 23 hypermethylated genes and 4 hypomethylated genes (CACNA2D4;LRTM2, ESPNL, SECTM1, PCDH8) for AA tumor samples; whereas, 29 hypermethylated genes and 1 hypomethylated gene (BRSK2) are listed for the CA tumor samples." (PMID 27111221, 2016). "In this analysis, we identified subtype‐specific events for Epi‐LumB tumors involving either DNA copy number loss or CpG promoter methylation over DZIP1, TNFSF11, ZIC5, COL4A2, COL4A1 and PCDH8 indicating candidate tumor suppressor genes." (PMID 25468711, 2015). "Similarly, PCDH8 acts as a cell adhesion molecule and tumor suppressor, and its hypermethylation promotes detachment, invasion, and reduced survival." (PMID 41377897, 2025).